STAT3 (signal transducer and activator of transcription 3)
Diseases named in the same sentence as STAT3 in open-access papers (continued):
Sharing a sentence is not in itself a finding about the gene and the disease.
cancer (continued). "Both STAT3 and Snail have proven roles in cancer metastasis." (PMID 23919497, 2013). "IL-6 is a Stat3 activator and is elevated in diverse cancers." (PMID 24453427, 2013). "The JAK/STAT3 pathway widely reported as a potent pro-survival and pro-metastatic signaling axis, and novel agents that specifically inhibit its activation offer a novel targeted therapeutic approach for many cancers." (PMID 24324713, 2013). "Although the role of STAT3 signaling in cancer stem or cancer-initiating cells is still unknown, this pathway might represent an attractive therapeutic target." (PMID 24376586, 2013). "In addition, research studies have suggested that many cancer preventive agents mediate their effects through inhibition of NF-kB and STAT-3." (PMID 23805101, 2013). "STAT3 activation is common in human cancers including both hematological and solid tumors." (PMID 23658720, 2013). "JAK/STAT3 pathway is involved in cancer, immune response, ischemia and cellular stress." (PMID 23967200, 2013). "As reported, EGFR and phosphorylated STAT3 were strongly expressed in the nucleus of cancer cells in surgical and biopsy specimens of nasopharyngeal tissues from NPC patients in southern China, suggesting that EGFR- and STAT3-dependent mechanisms are important for carcinogenesis." (PMID 24499623, 2013). "There is evidence implicating IL-6 in cancer tumorigenesis through the STAT3 pathway." (PMID 23819063, 2013). "Our cell line might also be valuable for finding compounds other than just those that inhibit STAT3 in cancer." (PMID 23950841, 2013). "Persistent STAT3 activity may contribute to many cancer progressions, most of which show JAKs, Src or Receptor Tyrosine Kinase abnormalities." (PMID 23704931, 2013). "We have previously shown that IL-6/Stat3/VEGF pathway plays an important role in cancer metastasis." (PMID 26082317, 2013). "A novel autocrine loop (IL-6/STAT3/HIF-1α) that operates in cancer cells was recently discovered." (PMID 24314323, 2013). "Aberrant activation of FGFR3 and STAT3 has been observed in a multitude of human cancers." (PMID 24115909, 2013). "Therefore, suppression of STAT3 activation should be a promising approach in the development of anti-cancer therapies." (PMID 23800091, 2013). "Similarly, elevated STAT3 expression and/or phosphorylation are observed in the majority of human cancers." (PMID 24312439, 2013). "In addition, we found reversed phosphorylated STAT3 status, another target of these TKIs in different cancer types." (PMID 23781255, 2013). "STAT3 is known to promote anti-apoptotic signals in many cancer types." (PMID 24025152, 2013). "It would be of interests to examine whether STAT3 is also activated in cancer stem cells from other types of human cancer." (PMID 24376586, 2013). "STAT3 was also described as a downstream target of Src kinase in cancer cells." (PMID 24165129, 2013). "STAT3 and 5 are persistently activated in many human cancer cell lines." (PMID 24308725, 2013). "Our study clearly showed that CD44 interacts with STAT3 then possibly transduces the signals through STAT3-hTERT pathway, which may activate Wnt signaling in the cancer stem cell population." (PMID 24386318, 2013). "Both STAT3 and Akt are important protein kinases contributing to either oncogenic or nononcogenic chemodrug resistance that fosters generation of the cancer stem cells or selection of the fast growing cancer cells." (PMID 24280348, 2013). "In addition to the activation of NF-κB, exposure to gDNAOX results in the upregulation of STAT3, known to promote the development and progression of some types of cancers." (PMID 24147001, 2013). "As such, it may be useful to consider intensifying the research on the signaling pathway of STAT3, in view of its importance in many cancers." (PMID 23857432, 2013).
cancer (continued). "Phosphorylated STAT3 translocates to the nucleus and initiates the transcription of genes regulating cellular proliferation, angiogenesis, survival, metabolism and immune modulation, which, when persistently activated, are hallmarks of cancer." (PMID 24312439, 2013). "Our previous results suggest that SHP-1-dependent STAT3 inhibition is a target of sorafenib and that the activated function of SHP-1 phosphatase that targets STAT3 may be a promising candidate for targeted cancer therapy and drug discovery." (PMID 23938089, 2013). "Indeed, STAT3 is well known to be part of a pro-inflammatory loop involving IL-6 and NF-kB, thought to play an important role in inflammation-related cancer as well as in auto-immunity." (PMID 23460527, 2013). "Our data reveals that RAS/MAPK signaling pathway that is connected with STAT3 signaling pathway might be the central mitogenic pathway negatively regulated by IL-23R in transformed or cancer derived mammalian cells." (PMID 24351840, 2013). "The oncoprotein Stat3 is constitutively activated in cancer cells in various types of human cancer." (PMID 23340652, 2013). "The activation of STAT3 is considered to be significant for cancer progression." (PMID 24260055, 2013). "Because of this oncogenic potential, STAT3 has been studied as a therapeutic target for cancer." (PMID 23950841, 2013). "STAT3 drives cancer cell proliferation, survival, invasion, and metastasis, and also has been implicated in chemoresistance; thus, c-Abl/Arg may drive doxorubicin resistance by activating STAT3." (PMID 23383209, 2013). "Collectively, these lines of evidence have validated STAT3 as a target for cancer therapy." (PMID 24199193, 2013). "Importantly, we further generated a series of sorafenib analogues that are devoid of raf-1 kinase inhibition, including several with promising anti-cancer potential due to their demonstrated p-STAT3 inhibition." (PMID 23938089, 2013). "Heightened activation of NF-κB and STAT3 are also significant promoters of cancer." (PMID 23894411, 2013). "Thus, inhibition of constitutive STAT3 activity by synthetic direct inhibitors or the JAK2 inhibitor AG490 has been shown to induce apoptosis of cancer cells." (PMID 24260381, 2013). "NF-κB activity dramatically decreased by STAT3 RNAi in many STAT3 constitutive activated cancer cells, suggesting that STAT3 inhibitors may also play potential roles in blocking NF-κB activity and enhancing growth inhibition in these cancer cells." (PMID 23704931, 2013). "Therefore, inhibiting cell proliferation and/or promoting apoptosis by suppression of STAT3 activation has been a major focus in the development of anti-cancer drugs." (PMID 22754353, 2012). "Targeting STAT3 signaling may lead to the development of novel therapeutic approaches for human cancers." (PMID 22348037, 2012). "Indeed, CD44+/ALDH+ cells isolated from HNSCC exhibit increased radioresistance and reversal of this phenotype by a STAT3 signalling blocker restored radiosensitivity of cancer cells." (PMID 22333601, 2012). "STAT3 is known to interact with cytoskeletal structures and drugs used in cancer treatment, such as microtubule stabilizer paclitaxel and microtubule inhibitor vinorelbine that decrease the tyrosine phosphorylation of STAT3 and thus inhibit the expression of STAT3 target genes." (PMID 23189171, 2012). "Moreover, SFN inhibits multiple oncogenic signaling pathways often hyperactive in human cancers, including nuclear factor-κB, Akt, signal transducer and activator of transcription 3, and androgen receptor." (PMID 22970326, 2012). "Therefore, a re-balance of cell apoptosis and proliferation via regulating STAT3 pathway and its target gene expression has been a promising target for the development of anti-cancer therapies." (PMID 22754353, 2012). "Thus, in order to elaborate target-specific anti-cancer compounds, the specificity of hpdODNs to STAT3 needs to be enhanced." (PMID 22423663, 2012).
cancer (continued). "To address whether disruption of STAT3 will lead to chemosensitivity in cancer cells, we inhibited STATs activation with XZH-5 in the presence of other chemotherapeutic drugs." (PMID 23056374, 2012). "Inhibition of STAT3 by shRNA could suppress viability of cancer cells, and down-regulate the STAT3-target genes." (PMID 22348037, 2012). "Constitutive activation of STAT3, resulting in an unregulated increase in cell proliferation and reduction in cell apoptosis, is strongly correlated with the development of numerous types of cancer including CRC." (PMID 22754353, 2012). "Direct targeting of STAT3 in malignant tumors may represent another important therapeutic tool as STAT proteins are emerging as ideal targets for cancer therapy." (PMID 23028383, 2012). "Furthermore, HDAC inhibitors other than SAHA, such as trichostatin A (TSA) and AR-42, have also been reported to suppress STAT3 phosphorylation in various cancer cells." (PMID 22647614, 2012). "The establishment of FoxM1 as a STAT3 gene target could connect STAT3 signaling to cancer-related cellular processes, such as increased proliferation, survival and drug resistance." (PMID 23110199, 2012). "Taken together, the malicious cooperation formed by 14-3-3ζ and Stat3 may serve as the Achilles Heel of MM and many other cancers, providing new opportunities for therapeutic intervention." (PMID 22279540, 2012). "STAT3 has been shown to be involved in wound-healing and migration of cancer cells which may lead to invasion and metastasis." (PMID 23056374, 2012). "Thus, the anti-cancer activities of Icariside II can be exerted by its pleiotropic effects on the multiple targets including STAT3 as well as JAK2, Src, and anti-apoptotic bcl-2, bcl-xL, survivin and COX-2 in U937 cells." (PMID 22493659, 2012). "Our findings suggest that Hedyotis diffusa Willd may be a potential novel therapeutic agent for the treatment of cancers with constitutive activation of STAT3." (PMID 22754353, 2012). "However, AZD1480 has also been shown to inhibit the growth of cancer cell lines independently of STAT3 activation, particularly at higher doses, possibly due to off-target effects of the drug." (PMID 23056499, 2012). "The level of activated p-STAT3 elevates in a variety of malignant tumors." (PMID 23110625, 2012). "Second, we found that the STAT3 shRNA can alone reduce cell motility and viability of cancer cells." (PMID 22348037, 2012). "Although originally discovered as a protein involved in the pathway transducing a signal in response to interferon, STAT3 was not linked to cancer until it was shown to be essential for v-src mediated cellular transformation." (PMID 23244668, 2012). "The novel binding mode could prove useful for developing more potent inhibitors aimed at preventing dimerization of cancer target protein STAT3." (PMID 23251591, 2012). "OCT4 could activate multiple signaling pathways to control Survivin expression, such as the STAT3, myc and NFκB pathways, which is critical for cancer cell survival and antiapoptosis." (PMID 23185410, 2012). "Constitutive STAT3 activity is required for the growth of cancer cells." (PMID 23056374, 2012). "XZH-5 could also inhibit interleukin-6-induced STAT3 phosphorylation in cancer cell lines expressing low phosphorylated STAT3." (PMID 23056374, 2012). "It was concluded that curcumin is a potent agent in the inhibition of STAT3 with favorable pharmacological activity,and curcumin may have translational potential as an effective cancer therapeutic or preventive agent for SCLC." (PMID 22662257, 2012). "Some studies indicate the role of STAT3 in EGFR signaling in various cancers." (PMID 22824293, 2012). "Based on the recent study a small reduction in PTEN gene expression can trigger cancer susceptibility, the higher level of PTEN in SNU-668 would play an enhanced role as a negative regulator of STAT3 and mTOR, consequently resulting in more significant molecular change of signaling." (PMID 22159814, 2012).
cancer (continued). "Moreover, recent studies have revealed a critical role of STAT3 in maintaining EGFR-mediated cancer cell proliferation." (PMID 23118721, 2012). "Block of STAT3 Tyr705-phosphorylation might disrupt STAT3 dimer formation and transcriptional activity, therefore induce apoptosis of STAT3-positive carcinoma cells." (PMID 23145121, 2012). "Collectively, Activation of STAT3 in cancer cells plays an important role in liver tumorigenesis." (PMID 22136659, 2011). "Stat3 is a cytokine- and growth factor-inducible transcription factor that regulates cell motility, migration, and invasion under normal and pathological situations, making it a promising target for cancer therapeutics." (PMID 21595927, 2011). "Notably, during the cross-talk between cancer and inflammatory cells, Stat3 and NF-κB seem to be key transcription factors linking a mutual positive feedback loop and promoting cancer progression." (PMID 22162712, 2011). "Given the cumulative evidence supporting Stat3 as a potential therapeutic target in cancer and that there are ongoing clinical trials testing Stat3 inhibitors, our group has attempted to better understand the molecular mechanisms of Stat3 activity and the role of HGF/c-met in transducing its signal." (PMID 21595927, 2011). "Never-the-less, based on these results we suggest that targeting the HGF/c-met/Stat3 pathway could be an especially effective strategy for cancer therapy." (PMID 21595927, 2011). "The detailed activities of STAT3 in cancer are reviewed elsewhere." (PMID 22190972, 2011). "Constitutively active STAT3 contributes to oncogenesis through upregulation of genes coding for anti-apoptotic proteins, cell cycle regulators and angiogenesis stimulators, leading to increased survival and uncontrolled growth of cancer cells." (PMID 21779382, 2011). "It is no surprise then that the constitutive activation of the STAT3 pathway has been found in a variety of cancers and is typically associated with a poorer prognosis." (PMID 21526200, 2011). "However, in a wide range of human cancers, STATs, particularly STAT3 and STAT5, become activated constitutively, thereby driving increased expression of genes that directly lead to malignant cellular behavior." (PMID 21680956, 2011). "In addition, interferon also appears to downregulate STAT3—a critical progression marker in cancer cell survival, proliferation, angiogenesis, metastasis, and immune evasion." (PMID 22220281, 2011). "The dose-response related decrease of the proportion of ALDH+ cells in the DU145 and LNCaP-IL6 cell populations and induction of apoptosis of these cells upon galiellalactone treatment suggest that these cancer stem cell-like cells are sensitive to STAT3 inhibition." (PMID 21779382, 2011). "Gene expression profiles in such cells are likely to be representative of the genetic profile of a cancer cell with aberrant STAT3 expression, as compared to inducing STAT3 activity transiently using exogenous stimulation, such as IL-6 or transient transfection." (PMID 22046235, 2011). "Thus, it is possible that activation of the IFN-γ/STAT-1/IRF-1 pathways serves to counteract the constitutive activation of STAT-3 in some cancer cell lines in the context of metastatic melanoma." (PMID 21875439, 2011). "This indicates that targeting the STAT3 pathway by JSI-124 could be an effective treatment for these cancers." (PMID 21702955, 2011). "Therefore, TQ administration is a new approach that can enhance immunogenicity, reduce cell proliferation and increase apoptosis in cancer cells by suppressing STAT3 phosphorylation and Bcl-2/Bcl-XL expression." (PMID 22177381, 2011). "Through IL-6/STAT3 activation, skeletal muscle is induced to synthesize acute phase proteins, thus establishing a molecular link between the observations of high IL-6, increased acute phase response proteins and muscle wasting in cancer." (PMID 21799891, 2011).
cancer (continued). "STAT3, like NF-κB, is a key regulator of inflammatory processes and frequently activated in cancer." (PMID 21291541, 2011). "As survivin is a potential downstream target of JAK2/STAT3 pathway, we further explored whether Cuc IIa also inhibited cancer cell expansion by inhibiting JAK2/STAT3 activation." (PMID 21304528, 2011). "They demonstrated the role of STAT3 in IL6 mediated migration of the cancer cells through EMT." (PMID 22194851, 2011). "Stat3 is aberrantly activated in a majority of cancers of epithelial origin." (PMID 20478049, 2010). "Blocking constitutive STAT3 signaling in carcinoma cells by STAT3 antisense oligonucleotides, STAT3 small interfering RNAs (siRNAs), or stable transfection of dominant-negative STAT3 can inhibit cancer cells growth, invasion and metastasis, and induce apoptosis." (PMID 20712901, 2010). "By targeting Stat3, we may directly inhibit Stat3-dependent drug resistant mechanisms and inhibit Stat3-independent drug resistant mechanisms indirectly by decreasing IL-6 autocrine production in cancer cells simultaneously." (PMID 21122157, 2010). "Thus, we designed a series of biochemical and genetic studies of various established cancer cell lines and clinically isolated cancer cells to directly investigate the regulatory role of Stat3 on IL-6." (PMID 21122157, 2010). "Taken together, these data lend to an intriguing suggestion that suppression of NF-κB activation in combination with suppression of the B-raf/Mek/Erk/Stat3 pathway may be a useful strategy in the suppression of cancer progression." (PMID 20659317, 2010). "Our laboratory has been involved in STAT3 inhibition for cancer therapy for a number of years." (PMID 21029412, 2010). "In addition, when correlated with different histopathological grades in HPV16 positive cancer lesions, cases with more advanced histopathological grades had significantly higher expression of active STAT3." (PMID 20977777, 2010). "Additionally, the IL-6 signaling pathway involving STAT3 had a significant number of contributing methylated genes, a pathway recently found to play a significant role in cancer stem cell regulation." (PMID 20929579, 2010). "In that PPARγ agonists inhibit both NF-κB- and Stat3-mediated transactivation of target genes and both of these transcription factors play a prominent role in cancer progression (see Section 2.8 and references therein), it is a likely extension to consider a role for PPARγ agonists to target CSCs." (PMID 20204067, 2010). "Thus, agents that can inhibit NF-κB and STAT3 activation pathways have the potential to both prevent and treat cancer." (PMID 22069560, 2010). "Studies not directly investigating the role of Stat3 on the expression of IL-6 in cancer cells have found some evidence suggesting Stat3 may increase IL-6 expression." (PMID 21122157, 2010). "Hence, activation of Stat3 within the ACF epithelium of TLR2−/− mice appears to promote a rise in NFkB driven pro-cancer TH17 inflammatory pathway while suppressing TH1 immunity." (PMID 20885960, 2010). "Importantly, we can show that STAT3 plays an important role as a master metabolic regulator also in STAT3-dependent human cancer cell lines, offering new insights into its core role as a transcription factor in human cancer." (PMID 21084727, 2010). "Because Stat3 is constitutively active in many types of cancers, it is considered oncogenic." (PMID 20204067, 2010). "Activation of Stat3 signaling by various mitogens is prevalent in different types of cancers." (PMID 20204067, 2010). "We found that FLLL32 inhibited P-JAK2 (Y1007/1008) in some of the cancer cell lines, which may explain the inhibition of the STAT3 phosphorylation in those cancer cell lines." (PMID 20712901, 2010).